NAP1L2 (nucleosome assembly protein 1 like 2)
Description:
Histone chaperone (By similarity). Plays a role in the epigenetic regulation of gene expression during cellular differentiation, by regulating the acetylation status of histone H3 and therefore chromatin accessibility. Plays a role in the differentiation of neuronal cells (By similarity). Increased activity during aging may suppress osteogenic differentiation of bone marrow mesenchymal stem cells (BMSCs) and promote their senescence; recruits SIRT1 to deacetylate histone H3 'Lys-14' at the promoter of osteogenic genes.
Synonyms: BPX; MGC26243
Tractability: Antibody: the Human Protein Atlas places it where antibodies can reach. PROTAC: ubiquitination databases record sites on it.
Gene: Protein-coding gene on chromosome X (73,212,299 to 73,215,239, reverse strand). Ensembl gene ENSG00000186462.
Subcellular location: Nucleus; Chromosome; Cytoplasm, cytosol
Subcellular location (Human Protein Atlas): Cytosol; Plasma membrane
Gene Ontology:
Molecular function: protein binding; chromatin binding; histone acetyltransferase regulator activity; histone binding
Biological process: epigenetic regulation of gene expression; neuron differentiation; nucleosome assembly
Cellular component: cytosol; plasma membrane; chromatin; nucleus; chromosome
Homologues: Orthologues: macaque NAP1L2 (97% identical), rabbit NAP1L2 (87% identical), pig NAP1L2 (86% identical), mouse Nap1l2 (84% identical), rat Nap1l2 (83% identical), zebrafish nap1l4a (31% identical), Drosophila melanogaster Nap1 (26% identical), Caenorhabditis elegans nap-1 (22% identical), Drosophila melanogaster CG3708 (22% identical), Drosophila melanogaster mil (19% identical), zebrafish tspy (14% identical), Caenorhabditis elegans spr-2 (13% identical), and 1 more. Paralogues in human: NAP1L1 (40% identical), NAP1L3 (35% identical), NAP1L4 (34% identical), SETSIP (16% identical), TSPYL4 (15% identical), SET (14% identical), TSPYL2 (14% identical), TSPYL1 (14% identical), TSPYL5 (14% identical), TSPYL6 (13% identical), NAP1L5 (11% identical), TSPY1 (10% identical), and 6 more.
Diseases named in the same sentence as NAP1L2 in open-access papers:
NAP1L2 is named in the same sentence as 15 diseases in open-access papers, as found by Europe PMC text mining. Sharing a sentence is not in itself a finding about the gene and the disease. The quoted sentences say what the papers report.
diabetic cardiomyopathy (2 papers, 2023 to 2024). Diabetic cardiomyopathy is a disorder of the heart muscle in people with diabetes. "In myocardial fibroblasts, high expression of periosteal protein upregulates nucleosome assembly protein 1-like 2 (NAP1L2) to deacetylate enzymes related to BCAA catabolism, which promotes cardiac fibrosis in diabetic cardiomyopathy." (PMID 38596692, 2024).
experimental autoimmune encephalomyelitis (2 papers, 2024). An autoimmune demyelinating disease of the central nervous system that is produced experimentally in animals by the injection of homogenized brain or spinal cord in Freund's adjuvant. "Besides, when BMSCs were transplanted in mice with experimental inflammatory bowel disease (IBD) or experimental autoimmune encephalomyelitis (EAE), the therapeutic efficacy of BMSCs was significantly decreased after Nap1l2 overexpression." (PMID 38348888, 2024).
autoimmune disease (1 paper, 2024). A disorder resulting from loss of function or tissue destruction of an organ or multiple organs, arising from humoral or cellular immune responses of the individual to their own tissue constituents. "The efficacy of BMSCs was reduced after overexpression of Nap1l2 in treating with autoimmune diseases IBD and EAE in mouse models." (PMID 38348888, 2024). "To investigate the impact of Nap1l2 on MSC in the treatment of autoimmune diseases in the nervous system, we constructed an EAE animal model." (PMID 38348888, 2024).
colorectal cancer (1 paper, 2024). A primary or metastatic malignant neoplasm that affects the colon or rectum. "However, there is no information on the role of NAP1L2, TONSL, HDAC9, and CHAF1B in colorectal cancer and were selected for further verification by qRT-PCR." (PMID 38212708, 2024).
diabetes (1 paper, 2023). "As expected, NAP1L2 downregulation rendered CF more invulnerable to HG-induced CF activation, as seen by lower fibrosis, oxidative stress, and inflammation, indicating that periostin is a positive regulator of NAP1L2, leading to CF activation in diabetes." (PMID 37993768, 2023). "The protein expression of SIRT1/3 was significantly elevated in CF upon HG exposure, yet, only the protein expression of SIRT3 was restored by silencing NAP1L2, indicating that NAP1L2 might affect SIRT3 to affect CF functions in diabetes." (PMID 37993768, 2023).
prostate carcinoma (1 paper, 2023). A carcinoma that arises from epithelial cells of the prostate gland. "We set ‘Gene’ as NAP1L2, set ‘TCGA tumor’ as prostate cancer tumor, set ‘TCGA normal’ as prostate cancer normal, and then performed co-expression gene analysis." (PMID 36195720, 2023).
senile osteoporosis (1 paper, 2022). "In vivo and clinical evidence from aging mice and patients with senile osteoporosis also confirmed that elevation of NAP1L2 expression was associated with suppressed osteoblastogenesis." (PMID 35032339, 2022). "Collectively, these in vivo and clinical data strongly demonstrate a close relationship between senile osteoporosis and NAP1L2 expression." (PMID 35032339, 2022). "Notably, when we isolated BMSCs from patients with osteoporosis, we also observed significantly higher NAP1L2 expression than those from age‐paired healthy controls." (PMID 35032339, 2022). "Finally, using an in vivo aging mouse model and clinical sample from patients with senile osteoporosis, we further validated the correlation of elevated NAP1L2 expression with the development of aging and impairment of BMSCs." (PMID 35032339, 2022). "We aim to clarify the role and mechanism of NAP1L2 in governing BMSC senescence and osteogenic differentiation through in vitro and in vivo experiments, as well as the correlation with senile osteoporosis in clinic." (PMID 35032339, 2022).
spina bifida (1 paper, 2011). A congenital neural tube defect in which vertebrae are not fully formed. "Mouse embryos with deletion of the Nap1l2 gene exhibit neural tube defects closely resembling spina bifida and anencephaly, and NAP1L2 may be related to X-linked neural tube defects in humans." (PMID 21738728, 2011).
neurodegenerative disease (2 papers, 2014 to 2025). A disorder of the central nervous system characterized by gradual and progressive loss of neural tissue and neurologic function. "In addition to Nap1l5, histone chaperone Nap1l2 regulates neuronal proliferation by interacting with chromatin while associated with AD among other neurodegenerative diseases." (PMID 40979532, 2025). "Comparison with aging brain data (3 patient cohorts, 221 samples) revealed 53 of these to be unique to neurodegenerative disease, many of which are strong candidates to be important in neuropathogenesis (e.g. NDN, NAP1L2)." (PMID 25187168, 2014).
tumor (2 papers, 2023 to 2024). "Among them, PHF19, AURKA, CHAF1B and AURKB were up-regulated in the tumor group, NAP1L2, TONSL, SATB2 and HDAC9 were down-regulated in the tumor group." (PMID 38212708, 2024). "Using qRT-PCR, we confirmed that SATB2, HDAC9, NAP1L2 expression was down-regulated in the tumor group." (PMID 38212708, 2024). "The analysis of showed that PHF19, AURKA, CHAF1B and AURKB were up-regulated in the tumor group, NAP1L2, TONSL, SATB2 and HDAC9 were down-regulated in the tumor group." (PMID 38212708, 2024). "Furthermore, NAP1L2 cooperated with YY1 to promote the transcription of MMP2 and MMP9, which promoted tumor metastasis." (PMID 36195720, 2023).
cancer (1 paper, 2022). A tumor composed of atypical neoplastic, often pleomorphic cells that invade other tissues. "Furthermore, we illustrated the expression of pyroptosis immune regulators across another∼10000 samples and revealed that CNST, GDF10, KCNC2, NAP1L2, NCOA7, and LINC00641 also revealed higher expression in cancer cells." (PMID 35620284, 2022).
NAP1L2 also shares sentences with these, for which no sentence is quoted: colitis (2 papers); breast carcinoma (1); inflammatory bowel disease (1); pancreatic neuroendocrine neoplasm (1).